CCL2 (C-C motif chemokine ligand 2)
Diseases named in the same sentence as CCL2 in open-access papers (continued):
Sharing a sentence is not in itself a finding about the gene and the disease.
osteosarcoma (continued). "The present study investigated the role of CCL2 in osteosarcoma cells." (PMID 25695619, 2015). "The mRNA and protein expression levels of CCL2 were upregulated in high-grade osteosarcoma cells." (PMID 25695619, 2015). "However, there is limited research on the role of CCL2 in osteosarcoma metastasis." (PMID 37893141, 2023). "Therefore, CCL2 represents a promising therapeutic target for treating metastasis in osteosarcoma." (PMID 37893141, 2023). "Consequently, CCL2 promoted both migration and invasion in osteosarcoma." (PMID 37893141, 2023). "It was also suggested that CCL2 may be important in osteosarcoma cells." (PMID 25695619, 2015). "Among the various chemokines secreted by osteosarcoma cells, including CCL2 (monocyte chemoattractant protein-1, MCP-1) plays a crucial role." (PMID 39949765, 2025). "In osteosarcoma, CD16+ monocytes/macrophages secrete chemokines CCL2, CCL3, and CCL8 to enhance tumor infiltration by immune cells." (PMID 41155410, 2025). "Osteosarcoma cells polarized macrophages to an M2 phenotype via CSF1 and CSF1R, and interactions between LYVE1+ and angiogenic macrophages through CCL2 and CCR1 promoted a proangiogenic niche and inflammatory responses." (PMID 40647416, 2025). "High concentrations of chemokines such as CCL2, CXCL12, and CXCL5 are produced by osteosarcoma cells, which bind to receptors on MDSCs and stimulate their migration into the TME." (PMID 39949765, 2025). "Many factors that play significant roles in neutrophil migration have been explored in osteosarcoma, including CXCL1, IL-6, CCL2, and so on." (PMID 39582869, 2024). "At one month following tumor-clearing CAR T cell therapy, the aggressive osteosarcoma model exhibited persistently elevated serum levels of CCL11, CCL2 and BAFF compared to tumor-bearing, mock T cell-treated control mice." (PMID 38798554, 2024). "The aim of this study is to examine the role of miRNAs in CCL2-mediated MMP expression and cell motility in human osteosarcoma." (PMID 37893141, 2023). "In conclusion, our findings have revealed that CCL2 downregulates the expression of miR-3659, consequently increasing the expression of MMP-3, thereby promoting osteosarcoma cell motility." (PMID 37893141, 2023). "The in vivo lung metastatic osteosarcoma model also demonstrated similar effects, showing higher levels of CCL2 and MMP-3 in lung metastatic osteosarcoma tissues." (PMID 37893141, 2023). "In this study, we observed higher levels of CCL2 and MMP-3 expression in lung metastatic osteosarcoma tissues compared to normal lung tissues." (PMID 37893141, 2023). "Next, we further examined the expression levels of CCL2 and MMP-3 in metastatic osteosarcoma tissues in vivo from our previous study." (PMID 37893141, 2023). "Both CCL2 and MMP-3 were highly expressed in lung metastatic osteosarcoma tissues compared to normal lung tissues." (PMID 37893141, 2023). "Monocyte chemoattractant protein-1 (MCP-1, also called CCL2) expressed by osteosarcoma participated in the regulation of macrophage recruitment and infiltration via the MCP-1/CCR2 axis." (PMID 33363016, 2020). "Tumor cells, including osteosarcoma cells, and cells in the tumor microenvironment, including fiboclasts and endothelial cells, secret monocyte chemotactic protein-1 (MCP-1/CCL2)." (PMID 25695619, 2015). "We found higher levels of CCL2 expression in human metastatic osteosarcoma samples with non-metastatic osteosarcoma or normal healthy bone samples." (PMID 37893141, 2023). "The correlation between CCL2 and MMP-3 was found to be positive in osteosarcoma." (PMID 37893141, 2023). "To investigate whether HOXA11-AS regulates CCL2 and CCR2, we transfected siHOXA11-AS into PC3 cells and the human osteoblastic osteosarcoma cell line SaOS2." (PMID 33514011, 2021). "Therefore, CCL2 and MMP-3 are highly expressed in metastatic osteosarcoma in vivo." (PMID 37893141, 2023). "However, it is not clear which miRNA regulates MMP3 in CCL2-induced osteosarcoma cell motility." (PMID 37893141, 2023).
osteosarcoma (continued). "More importantly, our Affymetrix Gene Chip results also demonstrated that the expression of MCP-1(CCL2) was not significantly changed after TIPE1 transfection, demonstrating that there might be other more important mechanisms involved in TIPE1-mediated osteosarcoma tumorigenesis and progression." (PMID 36151091, 2022).
glaucoma (35 papers, 2011 to 2025). Increased pressure in the eyeball due to obstruction of the outflow of aqueous humor. "Elevated CCL2 is implicated in greater risk of scarring in glaucoma surgery." (PMID 30456449, 2019). "A high concentration (1000 ng) of MCP-1/CCL2 exacerbated RGC loss in an experimental glaucoma model; 100 ng MCP-1/CCL2 provided neuroprotection towards RGC." (PMID 31355256, 2019). "In addition to IL-8 and CCL2, a broader spectrum of pro-inflammatory cytokines is elevated in different types of glaucoma." (PMID 40353220, 2025). "CXCL8 and CCL2 are pro-inflammatory cytokines that are elevated in various forms of glaucoma." (PMID 35456925, 2022). "In patients with glaucoma, the levels of chemokines of macrophage chemoattractant protein-1 (MCP-1), CXCR3, CCL2, and CCL7 show prognostic value and are correlated with disease progression." (PMID 34975917, 2021). "The other examples are CCL2, IL7, CXCR3, and CXCL12, which are found in scleritis, dry eye disease, glaucoma, dry eye disease, and Sjögren’s syndrome." (PMID 31810226, 2019). "Expression of proteins enriched in the vitreous (CCL2, IGFBP2, MMP10, HGF, TNFRSF11B (OPG)) was localized by immunohistochemistry in eyes of patients with severe ischemic CRVO followed by secondary glaucoma." (PMID 25978399, 2015). "To determine whether CCL5, like the β-chemokine Ccl2, is involved in retinal neurodegeneration and specifically in glaucomatous degeneration of RGCs, we examined CCL5 expression and localization in the DBA/2 model of glaucoma." (PMID 28936366, 2017).
parasitemia (34 papers, 2007 to 2024). "In agreement with this idea, mice deficient in CCR2, CCR5, CXCL9, CCL3, and CCL2 developed increased parasitemia and/or heart parasitism, whereas higher mortality was also observed in infected CCR5 and CCL2 KO mice." (PMID 37662946, 2023). "Utilizing confocal microscopy and intracellular flow cytometry, we identified microglia and brain-infiltrating myeloid cells as the main producers of CCL2 during acute infection, and CCL2 was specifically produced in regions of parasite infection in the brain." (PMID 38206985, 2024). "For other severe complications, such as severe anemia, higher MCP-1/CCL-2 levels were positively correlated with parasitemia in patients with P. falciparum or P. vivax infections." (PMID 39567619, 2024). "Similar to the CCR2-/- mouse, the CCL2/CCR2 double knock-out mouse is unable to clear parasitic infections despite higher than normal interferon-γ production than the CCR2 deficient mouse." (PMID 17888174, 2007). "Accordingly, CCL2 KO mice have reduced inflammatory foci and macrophage activation in the heart, despite increased systemic cytokine responses secondary to uncontrolled parasitemia and tissue parasitism." (PMID 37662946, 2023). "Based on MCP-1/CCL2 regulation of the migration and infiltration of monocytes and macrophages, an early type-1 response and elevated MCP-1/CCL2 in Mcpt4-/- relative to Mcpt4+/+ mice could explain the significant reduction in parasitemia in Mcpt4-/- mice." (PMID 35154114, 2022). "In addition, the lard diet promoted a higher parasites load in both evaluated sites evaluated with the distinct pattern of CCL2 expression, after 48 h of the peak of parasitemia concerning Colombian strain of T. cruzi." (PMID 34113663, 2021). "Besides clearing parasitemia, this treatment also resulted in a lower pulmonary mRNA expression of the inflammatory chemokines CCL2 and CXCL10, and of the cytokines tumor necrosis factor-α (TNF-α), IFN-γ, and IL-10." (PMID 33664739, 2020). "Since this and the other recognized glycoepitope, GalNAcβ1,4[Fucα1,3]GlcNAc (LDN-F), are present in parasitic helminths, CCL2 may be used for the diagnostics of parasitic infections in animals and humans." (PMID 22615566, 2012). "We demonstrated that even in the absence of symptomatic infections or asymptomatic urinary or parasitic infections, children with CZS have low CCL2 and CXCL8 production and increased serum levels of IFNγ and IL-13." (PMID 37766239, 2023). "We found a significant increase in CCL2 levels at d3, and an increase in CCL3 levels at d3 and d5 following parasitic infection." (PMID 36010615, 2022). "During L. monocytogenes infection, CCL2 levels were higher and increased already at d1 post infection (p.i.), while CCL3 levels were lower than during parasitic infection or in naïve mice." (PMID 36010615, 2022). "The clear upregulation of CCL2, CCL12 and CCL11 after parasitic infection implies an additional importance in eosinophil mobilisation." (PMID 34310619, 2021). "We analyzed parameters related to parasitemia, plasma levels of TNF, IL-10, and CCL2, and cardiac histopathology after the administration of carvedilol for 30 days." (PMID 28377930, 2017). "We observed a huge upregulation of CCL2/CCL7 serum levels and an increase in Ccl2/Ccl7 transcription in the BM at peak parasitemia." (PMID 23762028, 2013). "Of note, the perturbation of the liver damage parameters ALT, AST, total bilirubin, and also MDP values of IL-4, IL-6, IL-8, IL-12p70, CXCL9, CCL5, CCL2, CRP, fibrinogen and parasitemia levels showed an inverse correlation with the time living in the endemic area." (PMID 34727121, 2021). "Higher levels of some pro-inflammatory mediators such as IL-6, MCP-1/CCL2 and IP-10/CXCL10 were observed in P. vivax-infected patients, which were re-established after anti-malarial treatment, suggesting that the parasite infection triggered an inflammatory response." (PMID 28118834, 2017).
parasitemia (continued). "However, in our experiments the treatment with anti-CCL2 did not impact in parasitemia or survival rate." (PMID 31356587, 2019). "We observed that the treatment with anti-CCL2 antibody had no impact on the protective effect of ASP2 vaccination, as parasitemia levels remained lower compared to the ASP2+T." (PMID 31356587, 2019). "JG single infected mice presented reduced parasitemia and heart parasitism, no mortality, levels of pro-inflammatory mediators (TNF-α, CCL2, IL-6 and IFN-γ) similar to those found among naïve animals and no clinical manifestations of disease." (PMID 20967289, 2010).
preeclampsia (34 papers, 2007 to 2025). Preeclampsia is a hypertensive disorder of pregnancy that is characterized by new-onset hypertension with proteinuria presenting after 20 weeks of gestation, and depending on mild or severe forms may initially present with severe headache, visual disturbances, and hyperreflexia. "While CCL2 is essential for maintaining a successful pregnancy, elevated CCL2 levels have been associated with pathological conditions such as preeclampsia." (PMID 40943115, 2025). "Collectively, hypoxia in the placenta induces downregulation of ACKR2 and CCL2-related inflammation, leading to preeclampsia and probably fetal loss." (PMID 35677043, 2022). "ACKR2 deficiency promotes cellular apoptosis and elevates CCL2 levels, while increased apoptotic trophoblasts in preeclampsia may enter maternal circulation, triggering systemic inflammation." (PMID 41463301, 2025). "Among these genes, abnormal CCL2 level was associated with preeclampsia." (PMID 40216654, 2025). "However, abnormal levels of CCL2 have also been reported to be associated with adverse pregnancy outcomes such as spontaneous abortion, preeclampsia and preterm labor." (PMID 36685497, 2022). "Indeed, a number of genes regulated in this array were previously found to be associated with pregnancy complications such as preeclampsia (MR, CCL2, IGF-1, secreted phosphoprotein (SPP)-1, MMP-9), preterm labour (CCL18) and intrauterine growth restriction (IGF-1)." (PMID 18446208, 2008). "Targeting the CCL2/CCR2 axis presents a promising therapeutic avenue for preeclampsia, though achieving cell-specificity to avoid disrupting beneficial monocyte functions remains a significant challenge." (PMID 41463301, 2025). "Another interesting study reported that E2 reduced the level of CCL2 in the placenta to control inflammation and further treat preeclampsia (PE) via estrogen receptor Α36 (ERΑ36)-induced toll-like receptor 4 (TLR4) pathways." (PMID 36685497, 2022). "This explanation is consistent with the in vitro discovery of increased ACKR2 expression but decreased CCL2 scavenging in cytotrophoblast membranes separated from preeclampsia placentae." (PMID 35677043, 2022). "In preeclampsia, systemic inflammatory responses are mediated by chemokines (CCL2, CCL7, and CCL11), cytokines (IL-6), leukocytes, the coagulation cascade, and the complement system." (PMID 35677043, 2022). "Study has reported that patients with preeclampsia presented lower serum levels of CCL2." (PMID 40216654, 2025). "However, when exogenous infections or endogenous changes disorder the level of CCL2, impaired cell function and altered immunological tolerance will appear, leading to miscarriage, preeclampsia or preterm labor." (PMID 36685497, 2022). "As an association between sleep-disordered breathing, gestational hypertension, and preeclampsia has been demonstrated, CCL2 expressed and secreted from patient adipocytes may link between SAS and hypertensive disorders of pregnancy/gestational diabetes." (PMID 34884703, 2021). "Numerous studies have demonstrated that patients with severe preeclampsia exhibit elevated plasma levels of various chemokines—CXCL8 (IL-8), CCL2 (MCP-1), CXCL10 (IP10), and CXCL12 (SDF-1)—compared to healthy pregnant women." (PMID 41463301, 2025). "Of all the immune cell-regulated preeclampsia differential genes SLC9A9, SH2B3, SDC3, RCC2, F13A1, CCL2, and CBLB were consistently expressed in two transcriptome datasets, and all were highly expressed in macrophages." (PMID 40216654, 2025). "Lastly, we found that the SLC9A9, SH2B3, SDC3, RCC2, F13A1, CCL2, and CBLB in macrophages were likely to be correlated with preeclampsia." (PMID 40216654, 2025).
co-infection (33 papers, 2006 to 2025). "We believe CCL2 may potentially serve an attractive target of anti-fibrotic intervention against HIV/HCV co-infection associated co-morbidities." (PMID 25528160, 2014). "In contrast to the co-infection group, we found a weak positive correlation between CCL2 and CXCL8 (r = 0.21) in the HIV group." (PMID 37999614, 2023). "Increased proliferation of HIV in lung of persons with Mtb co-infection has been previously associated with increased TNF-α and CCL2 levels in bronchoalveolar lavage." (PMID 32373548, 2020). "Coinfection was hallmarked by extremely elevated concentrations of IL-10, as well as heightened levels of CCL2, in comparison to the distinct clinical presentations of P. vivax infections or HBV monoinfection." (PMID 31233500, 2019). "Further, considering one of the most common HIV/Mtb co-infection scenario, CCL2 is believed to exacerbate the disease pathogenesis by adversely affecting the natural history of both the pathogens." (PMID 25528160, 2014). "Furthermore, co-infection triggered the upregulation of Ccl2, Cxcl2 and Tnf, which were significantly less pronounced in comparison to GAS infection only." (PMID 36365071, 2022). "In addition, type I IFN production during IAV/bacterial coinfection has been shown to suppress CCL2, CXCL1, and CXCL2 levels and subsequently inhibit the recruitment of monocytes and neutrophils." (PMID 30420852, 2018). "IL-8, CCL2, and IL-6 were also remarkably increased in the co-infection group." (PMID 25906258, 2015). "Thus induction of CCL2 by both pathogens is an interesting aspect that needs to be addressed in a setting of HIV-1/Mtb co-infection." (PMID 24109479, 2013). "Furthermore, the expression of Ccl2 in lung samples that were taken at endpoints was comparable between bacterial infection and co-infection, which challenges the idea that IAV-induced alterations in immune cell recruitment continues after bacterial superinfection." (PMID 36365071, 2022). "An analysis of the serum levels of CCL2, CCL5, MIG, and IP-10 between co-infection and HIV patients highlighted higher levels of these chemokines in the HIV group." (PMID 37999614, 2023). "The chemokines CCL2, CCL5, MIG, and IP-10 exhibited higher levels in the HIV group compared to co-infection." (PMID 37999614, 2023). "Along these lines, we found in our study that CCL2 was significantly reduced in the plasma of IAV-infected mice and that both monocausal bacterial infection and co-infection featured Ifnb1 overexpression in the lung." (PMID 36365071, 2022). "Interestingly high CCL2 levels have also been linked with disease severity of TB patients Innate immunity is a key signature in our cohort, with an increase in both phenotypic and functional (cytokine producing) CD4+ and CD8+ semi-invariant Vα7.2+CD161+ cells in TB/Flu co-infection." (PMID 30662443, 2018). "In our study, expression of both CCL2 and VCAM-1 genes was significantly increased after co-infection of swine epithelial cells." (PMID 24708855, 2014). "In this review we highlight current view on the role of C–C chemokines, more precisely CCL2, on HIV-1: Mtb interaction, potential mechanisms of action and adverse clinical consequences in a setting HIV-1/Mtb co-infection." (PMID 24109479, 2013). "Taken together, this hypothetical model explains the CCL2 mediated on-going lung-specific HIV-1 and Mtb interplay and a mechanistic insight how HIV-1 and Mtb reciprocate each other in a setting of HIV-1/Mtb co-infection." (PMID 24109479, 2013). "Furthermore, higher levels of CCL2, CCL5, MIG, and IP-10 in the HIV group, and greater connectivity among the chemokines in the co-infection group, suggest that the Leishmania spp." (PMID 37999614, 2023). "Expression of CCL2 remained elevated in lung of animals with co-infection while moderate, though non-significant, reductions of IL-1β and IL-6 were observed compared to the TB group." (PMID 32373548, 2020).
co-infection (continued). "To examine the immune profile of individuals with co-infection, we compared the concentration of 15 immune markers (IL-1β, IL-6, IL-8, TNF-α, IL-7, G-CSF, MCP-1/CCL2, MIP-1-α/CCL3, IL-12, IFN-γ, IL-13, IL-17A, GM-CSF, IL-10, and TGF-β1) among the three groups using Kruskal-Wallis ANOVA." (PMID 27128316, 2016). "Thus, one can argue that both CCL2 and bacilli can affect the HIV-1 replication in HIV-1/Mtb co-infection scenario." (PMID 24109479, 2013). "In addition, we assessed inflammatory gene expression in the hippocampus, and whilst TNFα was significantly increased in co-infected mice, IL-6, IL-1β and CCL-2 were not altered by single- or co-infection treatment." (PMID 29980196, 2018). "The hypothalamus appeared to be particularly responsive to lung co-infection, as we did not observe any difference in microglial or astrocyte morphology in the hippocampus and whilst TNFα expression was increased, IL-6, IL-1β and CCL-2 expression were unaltered." (PMID 29980196, 2018).